TIGIT (T cell immunoreceptor with Ig and ITIM domains)
Diseases named in the same sentence as TIGIT in open-access papers (continued):
Sharing a sentence is not in itself a finding about the gene and the disease.
tumor (continued). "Our findings indicated that in TNBC, TIGIT (expressed in cells located in the microenvironment) can easily interact with its receptor PVR (expressed on tumor cells) to induce immunosuppression." (PMID 36544779, 2022). "In summary, Fc-FcγR interaction for PD-L1 and TIGIT blockades not only helped NK to deplete tumor cells and Tregs but also strengthened the cross-talking between T cells and antigen-presenting cells (APCs)." (PMID 36289396, 2022). "In clinical models, the combined blocking of PD-L1 and TIGIT can better recover the anti-tumor immune function than blocking PD-L1 alone." (PMID 34998385, 2022). "Here, we described the pre-clinical characterization of Ociperlimab (BGB-A1217), a novel humanized IgG1 anti-TIGIT antibody (mAb), and systemically evaluated the contribution of Fc functions in the TIGIT mAb-mediated anti-tumor activities." (PMID 35273608, 2022). "TIGIT interacts with several receptors on antigen-presenting cells (e.g. dendritic cells and macrophages) as well as on cancer cells and tumor microenvironment cells." (PMID 36544779, 2022). "The possible relationships between TIGIT expression and the tumor microenvironment (TME), infiltration of immune cells, immune-related genes, tumor mutation burden (TMB), and microsatellite instability (MSI) were revealed in this article." (PMID 36211383, 2022). "The expression of malignant tumor-infiltrating lymphocytes is significantly increased, making TIGIT a potential blockbuster target for cancer immunotherapy." (PMID 35958238, 2022). "Here, we studied the mechanisms whereby PD-1 and/or TIGIT blockade modulate anti-tumor CD8+ T cells." (PMID 35263569, 2022). "The highest expression of TIGIT on tumor infiltrating Tregs relative to other T cell subsets and the presence of NK and macrophages in the TME likely explains the preferential depletion of Tregs in tumors by BGB-A1217." (PMID 35273608, 2022). "Further, the expression level of immune checkpoint molecules (PDL1, CTLA4, LAG3, TIGIT, CD27, IDO1, ICOS) and tumor mutational burden (TMB) also showed significant differences between the two subtypes, indicating the clinical value of the two subtypes." (PMID 36568197, 2022). "Three classes of CD4+ T cells were identified via SCS, and it was found that CD4_1 upregulates TIGIT expression in tumors, CD4_2 expresses PD-1 (encoded by PDCD1) exclusively in tumors, and CD4_3 showed tumor-specific TIGIT and CD96 expression." (PMID 35785171, 2022). "Functional studies using orthogonal preclinical models revealed a synergistically antitumor response when TIGIT/PD-1 co-blockade was combined with CD40 agonism because they had been reinvigorated tumor-reactive T cells." (PMID 35656508, 2022). "Decreased tumor size and weight were also observed on day 21 after tumor challenge in mice treated together with anti-TIGIT mAb and single-injection low-dose OX." (PMID 36389751, 2022). "Here, we found that low-dose OX, an ICD-induced drug, increased the antitumor response of TIGIT blockade against CT26 tumor, which is regarded as a pMMR/MSS tumor." (PMID 36389751, 2022). "The TIGIT-Fc treatment enhanced effector NK cell functions and activated an anti-tumor T cell immune response via CD4+ T cells preventing their exhaustion." (PMID 35656508, 2022). "In contrast, blockade of TIGIT has been shown to prevent NK cell depletion and promote NK cell-dependent tumor immunity." (PMID 35911673, 2022). "We detected the expression of PD-1, LAG-3, TIM-3, and TIGIT on TILs and on tumor cells among 174 DLBCL patients by IHC." (PMID 36561512, 2022). "T-cell immunoreceptor with Ig and ITIM domains (TIGIT) participates in tumor immune escape by delivering inhibitory signals to T cells." (PMID 36211383, 2022). "TIGIT pathways induce, among other things, negative regulation of T cell-mediated tumor recognition and promotion of NK cell–dependent tumor immunity in different mouse models." (PMID 35078492, 2022).
tumor (continued). "A new development of 64Cu- and 89Zr-labeled antibodies targeting the T-cell immunoreceptor with Ig and ITIM domains (TIGIT) for immunoPET of TIGIT expression in the tumor microenvironment in tumor-bearing mouse models was reported." (PMID 35471681, 2022). "Combination therapy with anti-TIGIT and OX delayed tumor growth and prolonged overall survival significantly; nevertheless, anti-TIGIT or OX monotherapy was inefficacy." (PMID 36389751, 2022). "Similar to TIGIT, other inhibitory receptors on NK cells can be knocked out to restore the tumor-killing function of these cells." (PMID 35410257, 2022). "CD8+ T cells were stimulated with αCD3/CD28 and cocultured with tumour cells in the presence of an anti-TIGIT blocking antibody or isotype control." (PMID 35729552, 2022). "Given the regulatory role of the TIGIT pathway in T cell and NK cell-mediated tumor recognition, dual blockade of PD-1 and TIGIT effectively increases the expansion of tumor antigen-specific CD8+ T cells in vitro, promoting tumor rejection in a mouse model." (PMID 36612100, 2022). "The results indicate that Fc effector functions play critical role in the anti-tumor function of TIGIT antibody in vivo." (PMID 35273608, 2022). "There is growing evidence that the TIGIT blockade is a promising strategy that boosts the antitumor activity of NK cells even at advanced stages of the tumor." (PMID 36497240, 2022). "T cell immunoreceptor with Ig and ITIM domains (TIGIT), as a type of immune-checkpoint inhibitor receptor, is involved in the control of tumor immune surveillance." (PMID 36276117, 2022). "High expression of multiple inhibitory receptors expressed in reactive CD8+ T cells, and TIGIT in Tregs prompted the immunosuppressive tumor microenvironment in SS." (PMID 36400759, 2022). "Hong Kong scholars found that in HBV-HCC, TAM suppress tumor T-cell infiltration and regulate the immunosuppressive environment through TIGIT-NECTIN2 interactions." (PMID 36303541, 2022). "Twenty-one days after cell transfer, both tumor-infiltrating T cell populations expressed PD-1, Lag-3, Tim-3 and TIGIT (relative to naïve T cells in the spleen)." (PMID 35264436, 2022). "In 2018, Zhigang Tian lab found that the blockade of TIGIT reversed the exhaustion of tumor-infiltrating NK cells, increased the frequency of tumor-infiltrating NK cells expressing CD107a, tumor necrosis factor, interferon-γ, and CD226." (PMID 36289396, 2022). "Blockade of CD96 can enhance PD-1/PD-L1 and anti-TIGIT inhibition, leading to increased tumor regression and greater efficacy of immunotherapy." (PMID 36177001, 2022). "In the sepsis model of tumor-bearing mice, TIGIT was overexpressed on Treg and NK cells, binding to CD155 and mediating immunosuppression." (PMID 35433470, 2022). "As we have discussed in the previous sessions, activated or intra-tumor NK cells up-regulate checkpoint molecules (e.g., PD-1, TIGIT, TIM3, NKG2A) and blocked of those molecules unleash NK cell activity." (PMID 35967421, 2022). "In melanoma patients, dual blockade of TIGIT and PD-1 synergistically increased tumor infiltration and tumor antigen-specific CD8+ T cell proliferation, degranulation, and cytokine secretion, indicating the potential for dual blockade." (PMID 35606854, 2022). "TIGIT expression on tumour infiltrating lymphocytes (TILs) was reported in a variety of malignancies and negatively correlated with patient survival." (PMID 35806034, 2022). "The TIGIT/CD155 signaling pathway thus plays an important role in anti-tumor immunity, as it acts as an immune checkpoint capable of suppressing tumor-specific cytotoxic T/NK cell responses." (PMID 35327475, 2022). "We observed high expression of all NECTIN genes in tumor cells and TIGIT in Tregs and exhausted T cells, but noted substantial heterogeneity across cases." (PMID 35995947, 2022). "TBC1D10C also had a high positive association with tumor-infiltrating immune cells and common immune checkpoints (PD-1, CTLA-4, and TIGIT)." (PMID 35425695, 2022).
tumor (continued). "Single-cell analysis revealed that NECTIN family members, especially NECTIN4, are tumor-specific, uncovering a potentially targetable interaction with TIGIT in Tregs and exhausted T cells." (PMID 35995947, 2022). "Activated Treg cells express TIGIT infiltrating in the tumor microenvironment, which is related to poor survival." (PMID 35433470, 2022). "Although less well studied, CD226 is a costimulatory receptor regulated by TIGIT and exhibits multifaceted functions in anti-tumor CD8+ T cell responses." (PMID 35263569, 2022). "PVR on the tumor cell surface interacts with TIGIT and participates in the formation of an immunosuppressive tumor microenvironment by interacting with co-inhibitory receptors." (PMID 36552960, 2022). "On the other hand, similar to PD-1/PD-L1, TIGIT plays a role in inhibiting the tumor immune system and both are upregulated in different types of malignancies." (PMID 36276117, 2022). "Subsequently, we identified a hub gene, TBC1D10C, that correlated with OS and the PFI and had a high positive association with tumor-infiltrating immune cells and three common immune checkpoints (PD-1, CTLA-4, and TIGIT)." (PMID 35425695, 2022). "Previous studies have supported that dual the blockade of PD-1 and TIGIT mainly exerted effects on NK cells, thereby enhancing the anti-tumor activity of CD8+T cells." (PMID 35433470, 2022). "Binding to its ligands CD155 and CD112 (or nectin-2) expressed by tumor cells and antigen-presenting cells in the TME, TIGIT induces anergy of T cells and NKs, immune suppression, and tumor escape." (PMID 35712510, 2022). "One study showed that high TIGIT/DNAM-1 ratio in Treg cells found in tumor tissue demonstrated a correlation to poor clinical outcomes after treatment with anti–PD-1 ICB." (PMID 36059606, 2022). "Dual PD-1/TIGIT blockade potently increases tumor antigen-specific CD8+ T cell expansion and function in vitro and promotes tumor rejection in mouse tumor models." (PMID 35222404, 2022). "We analyzed bulk RNA-seq from NSCLC tumor samples from three randomized clinical trials with atezolizumab and assessed how gene expression of CD226, PDCD1 (encoding PD-1), and TIGIT associated with clinical outcomes." (PMID 35263569, 2022). "TIGIT is another cell surface inhibitor on NK cells and T cells, causing exhaustion of TIL and tumor-infiltrating NK cells." (PMID 36686835, 2022). "In preclinical models, the combination of anti-TIGIT and anti-PD-L1 synergistically improved tumor control and survival." (PMID 35712510, 2022). "Antibodies targeting TIGIT are currently being investigated in clinical trials to treat patients with different tumor types." (PMID 35164813, 2022). "Blocking TIGIT or its ligand poliovirus receptor leading to enhanced anti-tumor effects was observed in HER2 positive BC and TNBC cell lines." (PMID 33717059, 2021). "We also identified a subtype of proliferative T cells (Cluster 7 with high KI67 expression) which displayed both effector T-cell features (e.g., GZMA) and dysfunctional markers such as LAG3, TIGIT, and PD-1, indicating compromised tumor cytotoxic activity." (PMID 33144684, 2021). "Existing evidence has suggested that PVR can inhibit the function of NK cells via interacting with TIGIT, thereby suppressing the deteriorating effects against tumor cells." (PMID 34150627, 2021). "Abnormally expressed TIGIT suppresses immune cells in multiple steps of the tumor immune cycle and promotes tumor immune escape to a great extent." (PMID 34888386, 2021). "It has been shown that TIGIT and PD-1 blockade additively increased proliferation, cytokine production, and degranulation of tumor antigen-specific CD8+ T cells." (PMID 33568510, 2021). "Accordingly, surviving CD155-expressing MEL02 tumor cells suppressed T-cell activation, which was canceled by TIGIT blockade." (PMID 34795004, 2021).
tumor (continued). "We showed that the tumor cells infected with the oncolytic VV successfully expressed and secreted antibodies, which effectively bind to TIGIT in vitro." (PMID 33581644, 2021). "The antibody targeting TIGIT using alone or combing other antibodies has achieved significant anti-tumor effects." (PMID 33557880, 2021). "We found that VV-α-TIGIT showed enhanced anti-tumor immunity in several murine tumor models compared to control VV." (PMID 33581644, 2021). "TIGIT is expressed in several types of tumor cells and regulatory T cells; it is involved in immunosuppression and the immune evasion of cancer cells." (PMID 34143198, 2021). "TIGIT is another inhibitory molecule that has been found in several studies aimed at identifying genetic profile of tumor infiltrating T cells." (PMID 34025655, 2021). "The number of recruiting, not yet recruiting, active but not recruiting and completed clinical trials assessing the safety and efficacy of a human anti-TIGIT monoclonal antibody for tumor treatment continues to increase." (PMID 34433460, 2021). "TIGIT blockade does not only reinvigorate anti-tumor T cell responses but also enhances anti-tumor NK cell responses." (PMID 34367161, 2021). "The role of TIGIT in tumor immune surveillance is similar to that of the PD-1/PD-L1 axis in tumor immunosuppression." (PMID 34943817, 2021). "In the in vitro co-culture assays of T cells and tumor cells, the suppressed glucose metabolic activity of T cells was reversed by TIGIT blockade." (PMID 34659197, 2021). "Especially, inhibitory molecules TIGIT, CTLA4, and co-stimulatory molecules ICOS, CD28 whose expression was higher in tumor-associated Treg cells compared to that from normal tissues, were highly expressed in decidual Tregs." (PMID 34168655, 2021). "The role of TIGIT in tumor immune surveillance is analogous to the PD-1/PD-L1 axis in tumor immunosuppression." (PMID 34572764, 2021). "Of note, VV-α-TIGIT-treated mice showed a significantly lower proportion of tumor cells in the ascites compare to VV-Control-treated mice (P <0.05)." (PMID 33581644, 2021). "Red-A down-regulated CD155 expression in NSCLCs and unleashed NK cells to kill tumour cells, which shows the potential therapeutic value of developing checkpoint inhibitors targeting TIGIT/CD155 signalling." (PMID 33399495, 2021). "This study thus highlights the potential of targeting TIGIT immune checkpoint to restore immune T-cells’ anti-tumor functions." (PMID 33916641, 2021). "While single TIGIT blockade has limited anti-tumor efficacy, pre-clinical studies indicate that co-blockade of TIGIT and PD-1/PD-L1 pathway leads to tumor rejection, notably even in anti-PD-1 resistant tumor models." (PMID 34367161, 2021). "Full or conditional (specific deletion in NKp46-expressing cells, including NK cells) TIGIT deletion improved anti-tumor responses and survival of tumor-bearing mice compared to the wildtype group." (PMID 34885076, 2021). "In tumor-harboring mice, TIGIT deletion was demonstrated to protect against NK cell depletion and enhance prognosis." (PMID 34970253, 2021). "Anti-TIGIT antibody mediates the rescue of anti-tumor responses of effector T cells that requires the costimulatory signal of CD226." (PMID 34174928, 2021). "Similar to other checkpoint inhibitors, TIGIT was also involved in the anti-tumor target development." (PMID 34829838, 2021). "In cancer, co-expression of TIGIT and PD-1 has been observed in tumor infiltrated CD8+ T cells and its expression is increased in Tregs within Th subsets." (PMID 34025655, 2021). "Co-inhibition of TIGIT with anti-TIGIT antibody tiragolumab and anti-PD-L1 antibody atezolizumab restored functional tumour-specific T cells leading to greater ORR and progression-free survival in patients with non-small lung cancer." (PMID 33921181, 2021).
tumor (continued). "Herein, we analysed forty-three ccRCC tumour samples from COHORT 1 comprising the LAG-3 (n = 16), TIM-3 (n = 19), and TIGIT (n = 8) clusters for alterations in 160 cancer-associated genes." (PMID 34545095, 2021). "Other checkpoint inhibitors against CD96, TIGIT or TIM-3 enhance anti-tumor activity in various solid tumors." (PMID 34572387, 2021). "TIGIT inhibitory checkpoint molecule competes with activating DNAM1 receptor for the same ligands on tumor cells and in CRC patients it is more highly expressed on intratumoral NK cells than on peritumoral NK cells." (PMID 34858978, 2021). "The combined blockade of TIGIT and PD-1 had an add-on effect on the infiltration, cytokine production, and secretion of Granzyme B in tumor-specific T cells compared to the blockade of PD-1 alone." (PMID 34507594, 2021). "The tumor tissues with the upregulated expression of TIGIT also exhibited aberrant immune characteristics." (PMID 34795387, 2021). "TIGIT is a key checkpoint inhibitor in anti-tumour responses and thus presents a promising target for future immunotherapies." (PMID 33995362, 2021). "Blocking both TIGIT and PD-1/PD-L1 pathways enhances the expansion and function of tumor antigen-specific CD8+ T-cells." (PMID 34685400, 2021). "TIM-3, CTLA4, and TIGIT primarily trigger peripheral tolerance and promote tumor growth by inhibiting the activity of effector T cells." (PMID 33575321, 2021). "PVR binds to TIGIT, which is highly expressed in natural killer cells, T-cells, and regulatory T-cells, and induces immune escape of tumor cells." (PMID 33879814, 2021). "TIGIT is another inhibitory receptor co-expressed with PD-1 on tumor antigen-specific CD8+ T cells and CD8+ tumor-infiltrating lymphocytes (TILs)." (PMID 35070956, 2021). "There is also an almost uniform expression of the exhaustion marker TIGIT among the tumor-infiltrating Treg, while other immune checkpoint receptors associated with exhaustion (PD-1 and LAG3) were not expressed to any larger extent in the enriched clusters." (PMID 34407765, 2021). "CD155 is highly expressed in tumor cells and has high affinity to TIGIT, and induces IL-10 secretion, reduces the secretion of pro-inflammatory cytokines and inhibits antitumor response." (PMID 33747915, 2021). "Although not investigated yet, this observation suggests the possible combination of anti-TIGIT-mAbs with cetuximab, thereby reducing the suppressive action of Tregs and targeting specific tumor antigens." (PMID 34557197, 2021). "In contrast to DNAM-1, only marginal TIGIT expression is observed on resting NK and T cells while stimulation and tumor infiltration showed upregulated TIGIT expression." (PMID 34557197, 2021). "A triple combination of anti-TIGIT mAbs, anti-PD-L1 mAbs, and radiotherapy elicits almost complete remission of tumor growth in CT26-bearing mice." (PMID 33670993, 2021). "TIGIT was highly expressed in tumor-infiltrating CD8+ T cells from treated mice compared with that in the control." (PMID 34795004, 2021). "The co-inhibitory receptor TIGIT is also expressed upon T-cell activation to bind CD112, CD113, and CD155 ligands on APC and cancer cells; TIGIT inhibition can improve anti-tumor immune responses in vivo." (PMID 34639141, 2021). "Although the mice treated with VV-α-TIGIT only showed a trend of lower tumor volume compare to mice treated with VV-Control (P > 0.05), these mice demonstrated a significantly longer survival time than mice treated with VV-Control (P <0.01)." (PMID 33581644, 2021). "In mouse models of HNSCCs, TIGIT blockade delayed tumor progression through mechanisms involving CD8+ CTLs activation and Tregs inhibition." (PMID 33747915, 2021). "TIGIT inhibits NK cell-mediated tumor killing, induces immunosuppressive DCs, suppresses CD8 T cell priming and differentiation, and prevents CD8 T cell-mediated killing." (PMID 34025438, 2021).